SULT2B1 (sulfotransferase family 2B member 1)
Diseases named in the same sentence as SULT2B1 in open-access papers (continued):
Sharing a sentence is not in itself a finding about the gene and the disease.
SULT2B1 also shares sentences with these, for which no sentence is quoted: endometriosis (2 papers); adenomyosis (1); age-related macular degeneration (1); alcoholic cirrhosis (1); alopecia (1); atopic dermatitis (1); autosomal recessive congenital ichthyosis (1); coronary artery disease (1); gallbladder cancer (1); hyperlipidemia (1); liver steatosis (1); lymph node metastasis (1); melanoma (1); oesophagus cancer (1); prostatic intraepithelial neoplasia (1); Pruritus (1); schizophrenia (1); staphylococcus aureus infection (1); stomach adenocarcinoma (1).